CGAS (cyclic GMP-AMP synthase)
Diseases named in the same sentence as CGAS in open-access papers (continued):
Sharing a sentence is not in itself a finding about the gene and the disease.
infection (continued). "Nucleic acid-sensing mechanisms, such as the cyclic GMP–AMP synthase/stimulator of interferon genes (cGAS/STING) pathway, are essential to activate innate immunity in response to infection and have been co-opted by senescent cells to induce the SASP." (PMID 40645668, 2025). "At 48 hours (h) we confirmed infection and checked for markers of: senescence, virus induced DNA damage (VID), downstream activation of the cGAS pathway and expression of relevant antiviral chemokines and cytokines." (PMID 41139159, 2025). "In addition, Yptb WT and ΔtkeA(tkeA) infection could also induce cGAS activation." (PMID 40365777, 2025). "In this case, whilst the capsid protein was identified as responsible for cGAS degradation, STING expression remained unaltered during infection, although viral protein nsP1 was discovered to interact with STING." (PMID 39836220, 2025). "In leukocytes, expression of F13A1 (forming coagulation FXIII) correlated with TLR7, TLR9, RIG-I, MDA5, and LGP2, and with infection the correlations changed to TLR6 and CGAS." (PMID 40825056, 2025). "The cGAS-STING pathway has recently garnered attention for its role in mediating immune responses to cellular stress, DNA damage, and infection." (PMID 41227360, 2025). "Next, we analyzed the role of hnRNPM after infection with L. monocytogenes, herpes simplex virus type 1 (HSV-1), and Sendai virus (SeV), which are known to be sensed by cGAS, STING, and/or RIG-I." (PMID 39707025, 2025). "Briefly, cGAS senses DNAs from the host self and microorganisms to trigger the STING‐dependent innate immune response, preventing host from infection or maintaining self‐cells' stability." (PMID 38525112, 2024). "Intriguingly, while the cytosolic DNA sensor cGAS was upregulated in hMdM, STING (TMEM173) was downregulated after infection with IAV/PR8 in old macrophages." (PMID 39543713, 2024). "Recent studies indicate that the cGAS-STING pathway is an important immune response pathway in the organism and plays an important role in the regulation of pathological states such as infection and inflammation." (PMID 38904004, 2024). "Although detection of cGAS in SK6 cells was weak, a trend to reduction was observed at early times of infection while STING and tubulin seemed to follow a similar rate of decay." (PMID 38509419, 2024). "In this regard, our group described that the cGAS/STING pathway is only efficiently controlled by virulent ASFV strains, while attenuated ASFV strain infection leads to IFN-β production." (PMID 38675789, 2024). "STING agonists have been identified that induce cGAS-STING signalling prior to and during early infection of RNA viruses." (PMID 39411713, 2024). "Our data suggest that the cGAS/STING/TBK1 pathway promotes both an IFN-I response and viral IE gene expression following infection of THP1 monocytes, at least in the presence of VPA." (PMID 38932169, 2024). "Further, the cGAS-STING signaling pathway also emerged as a key mediator in inflammation and regulating infection, cellular stress as well as tissue damage." (PMID 38848144, 2024). "Immune evasion mechanisms, including cGAS/STING inactivation, allow for the chronicity of the infection." (PMID 38675916, 2024). "On the one hand, replication of DENV2, a DENV mutant, destroys host DNA, which induces cGAS-STING signaling and the IFN-I response, inhibiting the spread of infection." (PMID 38693578, 2024). "cGAS-STING has strict and fine regulations in space and time to ensure that while eliminating pathogen infection, it avoids damage to the body due to insufficient or excessive immune response." (PMID 40303074, 2024). "Apart from cGAS-STING pathway, many PRRs have been identified as taking part in sensing T. gondii during infection." (PMID 39457045, 2024). "Many sensor proteins (e.g., cGAS, AIM2, and TLR9) recognize the molecular signature of infection or stress and are responsible for the innate immune response to DNA." (PMID 38343534, 2024).
infection (continued). "During the later phases of infection, the SUMOylation of cGAS and STING is removed by SENP2 (sentrin/SUMO-specific protease 2), leading to degradation of cGAS and STING by the proteasome and chaperone-mediated autophagy (CMA), respectively." (PMID 39599852, 2024). "To further validate the role of cGAS-STING signaling in the control of IFNB and viral IE gene expression during infection, we used a small molecule inhibitor of cGAS activity, Ru.521." (PMID 38932169, 2024). "For example, infection with HSV‐1 and dengue virus (DENV) result in leakage of mtDNA into the host cell cytoplasm, rapidly activating the cGAS–STING‐dependent antiviral innate immune response." (PMID 38525112, 2024). "In this work, we have demonstrated that MGF505-2R, which is a late-expressed gene during the viral cycle, is able to counteract the activation of the cGAS/STING pathway and IFN-β production during infection." (PMID 38675789, 2024). "In the late stage of infection, SENP2 catalyzes the desumoylation of cGAS, making it polyubiquitinated and then degraded by the proteasome." (PMID 38525112, 2024). "Infection with KSHV activates various DNA sensors, including cGAS, STING, IFI16, and DExD/H-box helicases." (PMID 38793630, 2024). "Members of the cytoplasmic DNA sensing pathway included cyclic GMP-AMP synthase and STING, and the cGAS-STING pathway seemed to be able to detect KSHV in the initial stage of infection and latency reactivation of multiple cell types." (PMID 37242424, 2023). "After the first evidence of cGAS/STING antagonism by flaviviruses, STING activation has been detected following infection by various enveloped RNA viruses." (PMID 37077526, 2023). "cGAS is a PRR that senses exogenous DNA from bacteria or viruses and activates the innate immune system to fight against infection 37,38." (PMID 37554263, 2023). "The cGAS/STING pathway is involved in the response to several bacterial infections, but its role differs depending on the pathogen and the infection model." (PMID 37261352, 2023). "However, we interpret the magnitude of these effects with caution as unlike the specificity of ddC, EtBr indiscriminately intercalates into DNA and may therefore impact the quantity and/or quality of other DNA species that may also contribute to cGAS activation during infection." (PMID 38036506, 2023). "The homology between C5aR1 and C5aR2, and new proposed link to cGAS-STING signalling, provide rationale for further investigations C5aR2 in other infection scenarios." (PMID 38067135, 2023). "Various ISG mRNA was also activated by cGAS-STING stimulation and suppressed in the presence of EV-A71 infection." (PMID 36823147, 2023). "The cGAS-STING pathway is critical for the response to cellular damage that misplaces mitochondrial and genomic dsDNA, and for the response to infection by detecting microbial dsDNA." (PMID 37791071, 2023). "The DNA sensor cGAS (cyclic GMP-AMP synthase) and its adaptor protein STING (Stimulator of Interferon Genes) detect the presence of cytosolic DNA as a sign of infection or damage." (PMID 37534795, 2023). "During early stages of infection, IFI16 interacts with the viral DNA directly through its HIN domain which in turn enhances cGAS-mediated cGAMP production and TBK1 recruitment to STING." (PMID 36680267, 2023). "We focus on type I IFN induction through the cGAS-STING activation pathway in endothelial cells in context of autoinflammatory type I interferonopathies, inflammation and infection." (PMID 37791071, 2023). "The cGAS-dependent response induced by KSHV infection can limit infection, whereas KSHV also exhibits unique mechanisms to antagonize host cGAS sensing." (PMID 37600809, 2023). "The release of mtDNA from necrotic cells can activate the cGAS-STING pathway, a well-known inflammatory mediator triggered by mtDNA in response to infection, cellular stress, and tissue damage, leading to the induction of NETs formation." (PMID 37794018, 2023).
infection (continued). "Here, we show that DNA-PK is essential for cyclic GMP-AMP synthase (cGAS)- and stimulator of interferon genes (STING)-dependent IFN-I responses in human cells during stimulation with exogenous DNA and infection with DNA viruses." (PMID 38269102, 2023). "As IL-8 is activated by NF-kB,56 and we also discovered that the IL-8 promoter was also activated by cGAS-STING stimulation, but its activation was inhibited in the presence of EV-A71 infection." (PMID 36823147, 2023). "The titers of EV-A71 and FMDV were evaluated and compared in the WT and cGAS-/- mice, suggesting that the viral titers were significantly enhanced in cGAS-/- mice compared to that in WT mice during FMDV (left) or EV-A71 (left) infection." (PMID 36745686, 2023). "Infection by Pseudomonas aeruginosa induces mitochondrial damage and mtROS alongside the release of ox-mtDNA in a BAX-dependent manner that activates the cGAS, TLR9, and NLRP3 and NLRC4 inflammasomes." (PMID 37001140, 2023). "In summary, upon infection of ASFV, porcine cytosolic cGAS senses the dsDNA of virus and catalyzes the synthesis of the second messenger cyclic GMP-AMP 2’3’-cGAMP), which binds and activates the adaptor STING." (PMID 35437104, 2022). "Two outcomes of MOMP during infection, apoptosis versus mtDNA induction of IFN-I, are regulated by caspase-3 cleavage of cGAS and IRF3 (81, –, 83)." (PMID 35073751, 2022). "In this study, we aimed to determine the role of cGAS and STING in sensing Schistosoma-derived DNA and regulating of the process of S. japonicum infection using both cellular and mouse infection models." (PMID 35108342, 2022). "mtDNA stress promotes cGAS-dependent cytoplasmic mtDNA recognition, enhancing antiviral signaling and IFN-I responses during infection by activating STING-TBK1-IRF3 signaling." (PMID 35185917, 2022). "DNA damage induced cGAS/STING signalling and activated early type-I IFN response that inhibited infection dissemination." (PMID 36514984, 2022). "To investigate whether cGAS affects the type I interferon response during S. japonicum infection, we measured the mRNA levels of Ifnb1 in liver tissues and IFNβ in peripheral blood from wild-type mice and Cgas knockout (KO) mice at 4 and 7 weeks post-infection, respectively." (PMID 35108342, 2022). "In particular, the S. Typhimurium-induced Ifnb1 expression was attenuated in cGAS−/− or STING−/− PMs from 2 h.p.i, suggesting the cGAS-STING pathway was also involved in the initial activation of type I IFN response during infection." (PMID 35604097, 2022). "AECIIs directly sense VACV∆C7L infection and produce IFN-β and proinflammatory cytokines and chemokines through MDA5 and cGAS/STING-dependent nucleic acid-sensing pathways." (PMID 35351885, 2022). "DNA viruses have evolved many strategies to evade host type I IFN responses, predominantly the cGAS-STING axis, and facilitate the successful infection of host cells." (PMID 35861515, 2022). "For successful infection, DENV has evolved to curb STING activity whereby the NS2B3 protease cleaves STING to inhibit IFN induction while NS2B degrades cGAS." (PMID 36514984, 2022). "The expression of TRIM21, MDA5, cGAS, LGP2, and IFI44 was increased and the expression of RAS, GLOM2, HSP, FOX and TLCD4B was decreased in the foregut following SVCV infection." (PMID 36330521, 2022). "In this context, the cytosolic DNA sensor cyclic GMP-AMP synthase (cGAS), its downstream adaptor stimulator of interferon genes (STING) and the kinase TBK1 constitute a fundamental pathway critical for the outcome of infections." (PMID 36405710, 2022). "In case of infection, cellular stress, and tissue damage, the cGAS-STING signaling pathway senses DNA damage and regulates infection, inflammatory diseases, and tumor immunity." (PMID 36220835, 2022). "It has been shown recently that inactivated P. aeruginosa PAO1 vaccine stimulates the cGAS–STING pathway and protects elastase-induced COPD mice against subsequent PAO1 infection." (PMID 36359882, 2022).
infection (continued). "Interestingly, h-cGAS-Lys198 acetylation was found to be decreased by quantitative proteomics upon infection by either HSV-1 or HCMV (human cytomegalovirus), suggesting that these DNA viruses might evade innate-immune surveillance by hijacking acetylation of cGAS at these sites." (PMID 36139387, 2022). "The downstream cytokines regulated by cGAS-STING, especially type I IFNs, typically lead to induction of an antimicrobial state, activation of adaptive immunity, and eventual clearance of the infection." (PMID 36560581, 2022). "Inflammatory cytokines that induce the cGAS–cGAMP–STING signaling pathway, and are triggered by pathogen-derived DNA, are important in order to protect the host from infection." (PMID 36289904, 2022). "Previous studies showed that, upon infection, the HCMV tegument proteins pp65 or pp71 interfere with components of the cGAS/STING/IRF3 axis in order to evade the IFN response." (PMID 36552792, 2022). "To further dissect the role of the DNA sensor cGAS in the recognition of VZV, we developed a transwell‐based infection system." (PMID 35670106, 2022). "For example, during spreading infection in Jurkat T cells, which lack active SAMHD1 and cGAS, WT SIVmac and ∆vpx viruses replicate similarly, unless STING is activated with agonist (RR-S2 CDA), and then Vpx enhances infection, consistent with our data." (PMID 35073912, 2022). "Among these cellular DNA sensors, cGAS can sense HSV-1 DNA and trigger host immune responses upon infection." (PMID 34809467, 2021). "Of note, at 8 h post infection, SeV substantially stimulated phosphorylation of IRF3, a downstream protein for both RLR-MAVS and cGAS-STING pathways." (PMID 34732709, 2021). "The cyclic GMP-AMP synthase (cGAS)-STING pathway, which provides an innate immune antiviral response can be controlled by CMA especially in the late phase of infection." (PMID 34593046, 2021). "Our study revealed a novel and critical role of neddylation in the regulation of the cGAS-STING signaling pathway and provided a new perspective for restricting the infection of DNA pathogens." (PMID 33720974, 2021). "Mechanistically, infection with the bacterium, Francisella novicida, is sensed by the DNA sensor cyclic GMP-AMP synthase (cGAS)—stimulator of IFN genes (STING) pathway that activates type I IFN-dependent expression of IRF1." (PMID 33476326, 2021). "In the case of infection of host cells by many DNA viruses, DNA sensors such as TLR9 and cyclic GMP-AMP synthase (cGAS) are activated." (PMID 33593967, 2021). "The interplay between cGAS and IFI16 has been explored, revealing cooperation between IFI16 and cGAS upon infection (left)." (PMID 33981307, 2021). "We found that in control macrophages STAT1 was robustly phosphorylated at 4- and 6h post-infection, but phospho-STAT1 was undetectable in STING KO or cGAS KO macrophages at all time points." (PMID 34473814, 2021). "At 36-h post-infection, cells were treated with MG132 (5 μM) for another 12 h before collecting, then the ubiquitination level of cGAS protein was determined by Western blotting." (PMID 34394047, 2021). "E3 ubiquitin ligase TRIM41 is necessary for activating cGAS activity by monoubiquitination, and depleting this factor resulted in decreased IFN production and increased HSV-1 titers after infection." (PMID 34372578, 2021). "The cyclic GMP-AMP synthase (cGAS)-stimulator of interferon genes (STING) pathway is an important mediator of type I interferon and proinflammatory cytokine responses during infection and cellular stress." (PMID 34938294, 2021). "In the early phase of infection, PCV2 promotes the phosphorylation of cGAS at S278 via activation of PI3K/Akt signaling, which directly silences the catalytic activity of cGAS." (PMID 34543359, 2021).
infection (continued). "However, it should bear in mind that the activation of the cGAS-STING pathway may also increase the vulnerability to or severity of infections through dampening adaptive immunity, exacerbating inflammation or facilitating pathogen replication, survival, and infection." (PMID 33329537, 2020). "With regard to poxviruses, it has been demonstrated that Modified Vaccinia Ankara (MVA) infection of dendritic cells (DCs) triggers type I IFN production through a STING and cGAS-dependent pathway involving cyclic dinucleotides." (PMID 33154747, 2020). "Mutations in UL37 that interfere with its deamidase activity prevent this protein from inhibiting cGAS and lead to lower HSV-1 titers in the brain following infection." (PMID 33042875, 2020). "More studies are required to further explore the interconnection among these pathways and how cGAS/STING signaling toggles in transcriptional responses, different forms of RCD, anti-neoplastic transformation and anti-infection reactions." (PMID 35006429, 2020). "It is thus possible that the degradation of cGAS by CHIKV capsid is mediated via an intermediary interaction between cGAS-p62- and -capsid which results in both being degraded during infection." (PMID 33057424, 2020). "Infection of chicken macrophages with FWPV∆184 resulted in IFN and ISG transcription, which was lost in cGAS and STING CRISPR knockout lines." (PMID 33352813, 2020). "Upon infection with DNA viruses, STING is activated downstream of cGAMP synthase (cGAS) to induce IFN-I." (PMID 32182899, 2020). "Additionally, we investigated the expression levels of cGAS, which was found to be induced in all Tupaia at 28 days post-infection and partially induced at 31 weeks post-infection, suggesting that suppression of cGAS might have a role in the development of chronicity." (PMID 31842286, 2019). "To investigate a role for cGAS-induced T1-IFN during dermal VACV infection, we measured local tissue pathology in cGAS-/- mice compared to wild-type mice after intradermal infection of the ear." (PMID 31603920, 2019). "TBK1 plays a critical role as an integrator and inducer of RIG-I–MAVS, cGAS–STING, and TLR4–TRIF signaling pathways in response to infection by RNA viruses, DNA viruses, and bacterial LPS, respectively." (PMID 30769920, 2019). "The specific inhibitor of cGAS, Ru521, inhibits the activation of STING mediated by NH/P68 and Armenia/07 infection." (PMID 30918080, 2019). "Infection with the attenuated VACV strain MVA activated IRF-3 via cGAS and STING, and accordingly STING dimerized and was phosphorylated during MVA infection." (PMID 29491158, 2018). "As the host range of ECTV is restricted, we next investigated the roles of cGas and Sting in response to ECTV infection in murine cells." (PMID 29963044, 2018). "Subsequently, it was found that cyclic GMP-AMP synthase (cGAS), upstream activator of STING is required for activating type-I IFN production via the STING/TBK1/IRF3 pathway in this infection setting." (PMID 30463579, 2018). "A similar delivery vehicle has previously been shown to selectively activate cGAS- and STING-dependent immune recognition pathways, which are involved in innate immune sensing of HIV-1 during natural infection." (PMID 29378643, 2018). "To investigate the roles of murine cGas and Sting in response to the ECTV infection, we first compared the ability of ECTV to stimulate cGas-induced pathways in human cells." (PMID 29963044, 2018). "In PMA-differentiated THP-1 cells, MVA infection was sufficient to trigger IRF-3 activation, and this activation required cGAS and STING." (PMID 29491158, 2018). "Infection of retroviruses such as human immunodeficiency virus (HIV) generates RNA:DNA hybrids and dsDNA in the cytosol that can also activate the cGAS–STING pathway)." (PMID 30114241, 2018).